NR1I2 (nuclear receptor subfamily 1 group I member 2)
Description:
Nuclear receptor that acts as a transcription factor regulating genes involved in the metabolism and excretion of xenobiotics, drugs, and endogenous compounds. Activated by a broad range of endogenous steroids (e.g. pregnenolone, progesterone) and xenobiotics, including the antibiotic rifampicin and certain plant-derived metabolites. Upon ligand binding, translocates to the nucleus, forms a heterodimer with the retinoid X receptor/RXR, and binds to response elements in target promoters, leading to transcriptional activation. Target genes include cytochrome P450 enzymes such as CYP3A4 and ATP-binding cassette transporters including ABCB1/MDR1.
Synonyms: SXR; PXR; ONR1; BXR; PAR2; PAR; PAR1; PARq; PRR; SAR
Tractability: Small molecule: a structure with a bound ligand is known; a high-quality ligand is known; it has a high-quality binding pocket; it belongs to a druggable protein family. PROTAC: ubiquitination databases record sites on it; a small molecule that binds it is known.
Target class: Transcription factor; Nuclear hormone receptor subfamily 1; Nuclear hormone receptor subfamily 1 group I; Nuclear receptor; Nuclear hormone receptor subfamily 1 group I member 2
Chemical probes: hyperforin
Safety:
Unwanted effects reported when the protein is acted on. In parentheses: how it was acted on, where the effect was seen, and who reports it.
Increased, Liver Steatosis (activation; source: AOP-Wiki)
Loss, Cochlear function (activation; source: AOP-Wiki)
adverse events (source: ClinPGx)
adverse events bone marrow, gastro-intestinal and other toxicities (source: ClinPGx)
anemia (source: ClinPGx)
bone marrow and gastrointestinal toxicities (source: ClinPGx)
bone marrow and gastrointestinal toxicities or other adverse events (source: ClinPGx)
discontinuation due to neuropsychiatric adverse events (source: ClinPGx)
exposure (source: ClinPGx)
exposure to temsirolimus or sirolimus (source: ClinPGx)
flucloxacillin-induced liver injury (source: ClinPGx)
hypertension (source: ClinPGx)
metabolism of temsirolimus (source: ClinPGx)
severe anemia (source: ClinPGx)
Gene: Protein-coding gene on chromosome 3 (119,780,484 to 119,818,487, forward strand). Ensembl gene ENSG00000144852.
Subcellular location: Nucleus; Cytoplasm
Subcellular location (Human Protein Atlas): Nucleoplasm
Pathways (Reactome):
Gene expression (Transcription): Nuclear Receptor transcription pathway
Metabolism of proteins: SUMOylation of intracellular receptors
Gene Ontology:
Molecular function: DNA-binding transcription activator activity, RNA polymerase II-specific; nuclear receptor activity; nuclear receptor binding; protein binding; RNA polymerase II transcription regulatory region sequence-specific DNA binding; sequence-specific double-stranded DNA binding; DNA-binding transcription factor activity, RNA polymerase II-specific; RNA polymerase II cis-regulatory region sequence-specific DNA binding; DNA binding; DNA-binding transcription factor activity; sequence-specific DNA binding; zinc ion binding
Biological process: negative regulation of DNA-templated transcription; positive regulation of DNA-templated transcription; positive regulation of transcription by RNA polymerase II; regulation of DNA-templated transcription; xenobiotic catabolic process; xenobiotic metabolic process; xenobiotic transport; cell differentiation; cellular response to molecule of bacterial origin; intestinal epithelial structure maintenance; intracellular receptor signaling pathway; negative regulation of transcription by RNA polymerase II; signal transduction; steroid metabolic process
Cellular component: cytoplasm; nucleoplasm; nucleus; transcription regulator complex; chromatin
Genetic constraint (gnomAD): Loss-of-function variants: 42 observed, 46.17 expected, observed/expected ratio (o/e) 0.91, 90% interval 0.71 to 1.18. The upper end of that interval is the gene's LOEUF score, 1.18, which puts it in group 5 of 6, group 1 being the genes least tolerant of losing a copy. Missense variants: 559 observed, 596.4 expected, observed/expected ratio (o/e) 0.94, 90% interval 0.87 to 1. Synonymous variants: 229 observed, 227.88 expected, observed/expected ratio (o/e) 1, 90% interval 0.9 to 1.12.
Homologues: Orthologues: chimpanzee NR1I2 (98% identical), macaque NR1I2 (95% identical), pig NR1I2 (83% identical), dog NR1I2 (80% identical), mouse Nr1i2 (76% identical), rat Nr1i2 (76% identical), rabbit NR1I2 (73% identical), guinea pig NR1I2 (59% identical), zebrafish nr1i2 (46% identical), tropical clawed frog nr1i2 (46% identical), Drosophila melanogaster EcR (24% identical), Drosophila melanogaster Hr96 (22% identical), and 181 more. Paralogues in human: VDR (40% identical), NR1I3 (37% identical), NR1H2 (27% identical), NR1H3 (26% identical), NR1H4 (26% identical), NR1D1 (25% identical), NR1D2 (25% identical), THRB (25% identical), RARA (25% identical), RARB (24% identical), RORC (24% identical), RARG (23% identical), and 6 more.